SLC38A12 (solute carrier family 38 member 12)
Synonyms: TMEM104; FLJ20255; FLJ00021
Tractability: Antibody: UniProt predicts a signal peptide or a membrane-spanning region. PROTAC: ubiquitination databases record sites on it; its protein half-life has been measured.
Gene: Protein-coding gene on chromosome 17 (74,776,477 to 74,839,753, forward strand). Ensembl gene ENSG00000109066.
Subcellular location: Membrane
Subcellular location (Human Protein Atlas): Nucleoplasm; Golgi apparatus
Gene Ontology:
Cellular component: membrane
Genetic constraint (gnomAD): Loss-of-function variants: 39 observed, 48.11 expected, observed/expected ratio (o/e) 0.81, 90% interval 0.63 to 1.06. The upper end of that interval is the gene's LOEUF score, 1.06, which puts it in group 4 of 6, group 1 being the genes least tolerant of losing a copy. Missense variants: 684 observed, 705.2 expected, observed/expected ratio (o/e) 0.97, 90% interval 0.91 to 1.03. Synonymous variants: 311 observed, 296.43 expected, observed/expected ratio (o/e) 1.05, 90% interval 0.95 to 1.15.
Homologues: Orthologues: chimpanzee TMEM104 (97% identical), guinea pig TMEM104 (93% identical), rabbit TMEM104 (92% identical), pig TMEM104 (92% identical), macaque TMEM104 (91% identical), mouse Tmem104 (90% identical), rat Tmem104 (89% identical), dog TMEM104 (82% identical), zebrafish tmem104 (74% identical), tropical clawed frog tmem104 (74% identical), Drosophila melanogaster CG5262 (43% identical), Caenorhabditis elegans C03A3.2 (38% identical).